IL5 (interleukin 5)
Diseases named in the same sentence as IL5 in open-access papers (continued):
Sharing a sentence is not in itself a finding about the gene and the disease.
eosinophilia (continued). "Although inhibition of IL-5 activity in this manner (using mepolizumab) results in significant depletion of circulating eosinophils, the effect on bronchial tissue eosinophilia is less marked, with a median reduction of 55%." (PMID 28713812, 2017). "Over-production of TH2-related cytokines (IL-4, IL-13, and IL-5) in IgG4-RD tissues has previously been reported and correlates with IgE and IgG4 class switch, blood eosinophilia, and eosinophilic infiltrates that are common features of IgG4-RD." (PMID 28348556, 2017). "The use of anti-IL-5 therapies on patients with severe eosinophilic asthma has reduced asthma exacerbations and blood eosinophilia, see other article by Nair in this issue." (PMID 28971096, 2017). "IVE and AET treatment also decreased IL-4 and IL-13 mRNA expression in lung tissue, as well as eosinophilia and IL-4, IL-5, and IL-13 production in BALF." (PMID 29062168, 2017). "In response to viral challenge, IPS-1−/− mice developed a type-2 inflammatory response as indicated by a significant eosinophilia and lymphoplasia, together with increased production of IL-5 and IL-13 in bronchoalveolar lavage fluid (BALF)." (PMID 28539639, 2017). "Inflammatory responses to parasitic worms produce IL-5, which induces eosinophilia that in some models promotes parasite elimination and in others prevent effective immunity." (PMID 29163523, 2017). "Inflammation in AD is mediated by an initial Th2 phase, which is orchestrated by IL-4, IL-5, and IL-13 cytokines and is related to IgE production and eosinophilia." (PMID 28265582, 2017). "Although a role for IL-33 in the induction of IL-5 and eosinophilia was first proposed at that time, these effects were attributed to the production of IL-5 by Th2 cells." (PMID 28751971, 2017). "IL-5 induces bone marrow to produce eosinophils leading to tissue eosinophilia and airway remodelling." (PMID 28761563, 2017). "In a mouse model of allergic airways inflammation, allergen-induced lung tissue eosinophilia was abolished in mice bred to lack the common β-subunit, therefore incapable of responding to IL-3, IL-5, and GM-CSF." (PMID 28713812, 2017). "IL-5 is necessary for long-term eosinophilia, and is the major factor inducing eosinophil differentiation from lineage-committed precursors, after which it extends the lifespan of infiltrating eosinophils." (PMID 28046055, 2017). "In rats, N. brasiliensis infection induces eosinophilia and Th2 cytokines IL-4 and IL-5 between 7 and 14 days, after which these parameters return to normal by 28 days due to expulsion of the parasites." (PMID 29163523, 2017). "In OVA-treated WT mice, PM2.5 exacerbated OVA-related lung eosinophilia along with an increase in Th2 cytokines (IL-5, and IL-13) and chemokines (eotaxin and MCP-3) and infiltration of eosinophils into the airways." (PMID 28887522, 2017). "Treg-depleted mice showed increased mucus production, eosinophilia, IgE production, Th2 cytokines (IL-4, IL-5, IL-13), as well as increased fungal burden." (PMID 29333430, 2017). "For example, early work concluded that IL-33-induced eosinophilia was dependent on IL-5, but this conclusion was based largely on a neutralizing antibody approach and limited markers for defining eosinophils." (PMID 28512632, 2017). "Further phenotypic changes occurred during this IL-2/Jes6-1 treatment, namely an expanded population of IL-5+ ILC2 (Lin− ICOS+), associated eosinophilia and decreased CD11b+ Ly6G− Ly6Chi inflammatory monocytes." (PMID 28589929, 2017). "TPL-2 deficiency led to exacerbated HDM-induced airway allergy, with increased airway and tissue eosinophilia, lung inflammation, and IL-4, IL-5, IL-13, and IgE production." (PMID 27484038, 2017). "This is in contrast to the finding of high serum IL-5 levels—which are associated with eosinophilia in infants with CMA—in an earlier study, although after 2 weeks on a CM elimination diet, IL-5 became undetectable in that study." (PMID 28934137, 2017).
eosinophilia (continued). "Confirming these observations, blocking CD86 decreased Th2 immune responses, demonstrated by low IL-4 and IL-5 cytokines as well as low airway eosinophilia." (PMID 29333430, 2017). "Airway eosinophilia and the levels of IL-4, IL-5, and IL-13 were attenuated by the anti-CCL3 antibody." (PMID 27829417, 2016). "It has been demonstrated that helminth infections strongly induce an immune response involving elevated Th2 cytokines (i.e., IL-4, IL-5, IL-9, and IL-13), IgE, IgA, eosinophilia, and mucus secretion." (PMID 27882241, 2016). "Strikingly, RFP expression was found exclusively in ILC2s, indicating that ILC2-derived IL-5 is critically required for chitin-induced eosinophilia." (PMID 26965110, 2016). "In a mouse model, treatment with IL-16 systemically diminished the release of IL-5 and bronchoalveolar lavage eosinophilia." (PMID 27053925, 2016). "The only indication that ILC2-derived IL-5 is sufficient to induce eosinophilia came from a recent study that used IL-5 reporter (Red5) mice to investigate pulmonary IL-5 production." (PMID 26965110, 2016). "For example, similar to KB, oral exposure to live Lactobacillus reuteri bacteria can attenuate IL-5, IL-13 and eosinophilia in a mouse model of allergic airway inflammation, which was accompanied by a decrease in airway hyperresponsiveness." (PMID 27734946, 2016). "Preclinical studies have demonstrated a key role for IL-5 in murine models of allergen-induced airway eosinophilia and hyperresponsiveness." (PMID 27875559, 2016). "IL-4 is involved in induction of airway hyperresponsiveness and production of specific IgE and T cell-derived IL-5 is one of the key regulators of eosinophilia in lungs." (PMID 27795621, 2016). "The pathophysiology of eosinophilia in rheumatology patients is yet to be elucidated, although a reactive process secondary to increased circulating cytokines (especially interleukin-5) appears feasible." (PMID 27084779, 2016). "Our findings demonstrated that, at a basal state, eosinophilia in p110γ/δ-/- mice correlated with increased levels of IL-5." (PMID 27442134, 2016). "This corresponds with earlier findings on allergen-induced eosinophilia, which show that IL-5 promotes development and survival of eosinophils, whereas IL-13 mediates recruitment of eosinophils through secretion of eotaxins." (PMID 26965110, 2016). "Our observation that CF null eosinophils fail to accumulate normally during allergic inflammation is in agreement with studies showing that tissue eosinophilia arises due to delayed eosinophil apoptosis in response to survival signals such as IL-5." (PMID 27067058, 2016). "Then, even with little differences in the production of IL-4 and IL-12 by APCs, both protocols induced significant differences on IL-5 production and eosinophilia." (PMID 25973430, 2015). "On the other hand, chronic expression of IFN-γ has also been shown to enhance allergen induced eosinophilia, IL-5, and IL-13 expression and has induced side effects when administered to allergic patients." (PMID 26557723, 2015). "The Th2 immune response is characterized by the development of IL-4 and IL-5-producting effector T cells, which contribute to the allergic responses in several aspects, such as eosinophilia." (PMID 25960757, 2015). "IL-5 induces differentiation and proliferation of bone marrow eosinophils, promotes blood eosinophilia, activates eosinophils, and prolongs their survival." (PMID 26300589, 2015). "In asthmatics patients low dose theophylline reduce eosinophils and other inflammatory markers, inhibits the eosinophilia induced by an inhaled allergen and reduce the expression of cytokines such as interleukin-5." (PMID 27275306, 2015). "During an allergic response, IL-5 stimulates the differentiation of eosinophils from bone marrow cells and maintains cell survival resulting in blood eosinophilia." (PMID 25826377, 2015).
eosinophilia (continued). "These patients are distinct from neutrophilic refractory asthmatics as they have eosinophilia despite high dose steroid therapy and respond to anti-IL-5 antibody therapy." (PMID 26663987, 2015). "Anti-interleukin-4 and anti-interleukin-5 had been effective in reducing exacerbations and persistent eosinophilia in asthmatic patients." (PMID 26101464, 2015). "Eosinophilia in lung tissue is driven partially by the recruitment of eosinophils to the lung mucosa and interstitium due to airway produced IL-5, as well as production of eotaxin (CCL11), eotaxin-2 (CCL24), and eotaxin-3 (CCL26)." (PMID 26346739, 2015). "It has previously been shown that Sox4 transgenic mice exhibit decreased ovalbumin-induced allergic airway disease with lower AHR, IL-5, and eosinophilia." (PMID 26588780, 2015). "In a previous study, our group demonstrated that AT-RvD1 markedly decreased airway eosinophilia and mucus metaplasia, in part by decreasing IL-5 and IkBα degradation in allergen-sensitized and challenged mice." (PMID 26075216, 2015). "IL-5 induces eosinophilia activity and infiltration, which is the critical response in the allergic asthma." (PMID 26064160, 2015). "The reduced eosinophilia in the lungs of PS-F2-treated animals was most likely due to the reduced level of IL-5." (PMID 25019045, 2014). "The potential ‘responders’ to IL-5 therapy are patients who present with eosinophilia (blood >0.3 × 109/L, >3% sputum), are generally steroid-responsive, and suffer from frequent exacerbations." (PMID 25709744, 2014). "Many of the anti-IL-5 clinical trials document the presence of tissue eosinophilia in spite of nil/low circulating levels, post-treatment." (PMID 25709744, 2014). "Mice with high eosinophilia driven by IL-5-overexpression exhibited lower worm burdens following primary infection, with eosinophils and/or IL-5 likely mediating their action on migrating larval stages in the skin and lung." (PMID 25028340, 2014). "This is supported by a number of murine studies of allergic asthma which propose a dissociation between airway hyperresponsiveness and “traditional” TH2 measures such as IL-5, IgE and eosinophilia." (PMID 24632596, 2014). "TNF levels were slightly elevated (log scale) and, consistent with reports of eosinophilia in cpdm mice, IL-5 (a key inducer of eosinophil maturation) was also elevated." (PMID 25443632, 2014). "The allergic reactions to OVA in mouse airway typically evoke TH2 dominated responses with dramatically increased levels of IL-4, IL-5, and IL-13, which are accompanied by eosinophilia and IgE expression." (PMID 24755955, 2014). "IL-5 is critically involved in airway eosinophilia, it regulates most aspects of eosinophil behavior, including growth, maturation, adhesion,secretion and apoptosis." (PMID 24955743, 2014). "Cutaneous eosinophilia persisted in Sharpin−/−, Il4ra−/− mice, although expression of Il5 mRNA was reduced and the expression of Ccl11 and Ccl24 was completely abolished." (PMID 24465642, 2014). "While the Th2-type cytokine IL-13 can induce AHR independently of eosinophilia, ablation of eosinophils in a IL-5/eotaxin double knockout system abolishes AHR by reducing the ability of T cells to produce IL-13." (PMID 23378838, 2013). "Blockade of HIF-1α in vivo, significantly decreased allergic inflammation and eosinophilia induced by allergen, due to a reduction in the levels of IL-5 and Eotaxin-2." (PMID 23935964, 2013). "Other studies have shown that eotaxin plays an important role in initiating both blood and tissue eosinophilia in the early phase of allergic inflammation, while IL-5 is essential for eotaxin-induced tissue eosinophilia." (PMID 23378838, 2013). "As parasitic infestation is associated with Th2 responses and production of IL-5, that induces eosinophilia, one possibility is that this IL-5 promotes antigen specific Ts2 cells to control autoimmunity." (PMID 23935597, 2013).
eosinophilia (continued). "Recent studies have also shown a role of epithelial cell-derived cytokine thymic stromal lymphoprotein (TSLP), IL-25, and IL-33 in promoting eosinophilia by inducing IL-5 production." (PMID 23378838, 2013). "Increased secretion of IL-4 and IL-13 by T cells leads to antibody class switching (from IgG to IgE) by B cells, and IL-5 induces eosinophilia." (PMID 23451048, 2013). "In the gastrointestinal tract local IL-5 mediated eosinophilia has been shown to be central to oesophageal remodelling in eosinophilic oesophagitis." (PMID 23717571, 2013). "Allergic inflammation is characterized by increased Th2 cytokines including IL-4, IL-5, and IL-13 resulting in tissue eosinophilia, epithelial mucus metaplasia, and IgE production." (PMID 24876829, 2013). "The classic paradigm underlying allergic disease has been characterized by allergen specific Th2 cell production of IL-4, IL-5 and IL-13 leading to tissue eosinophilia, mucus production, and specific IgE production." (PMID 24876829, 2013). "Murine studies using IL-5 KO mice have shown that subcutaneous administration of eotaxin alone is insufficient to induce tissue eosinophilia." (PMID 23378838, 2013). "Further, infection with Helminth parasites ameliorates TNBS-induced colitis but exaggerates OXN-induced colitis via eosinophilia and elevated IL-5." (PMID 24348533, 2013). "The increased ILC2 expansion in IL-1β−/− mice correlated with increased early IL-5 and IL-13 cytokine production, helminth-induced eosinophilia and goblet cell hyperplasia." (PMID 23935505, 2013). "In our study, eosinophilia and levels of IL-5 decreased in older mice and correlated with reduced mucous cell metaplasia." (PMID 24138138, 2013). "With the advent of the genetic knockout era, the critical role of IL-5 and eosinophilia in controlling worm burden in mice was confirmed." (PMID 22360486, 2012). "In this study, probiotics were able, in a therapeutic manner, to significantly modulate allergic inflammatory markers such as lung eosinophilia and lymphocyte recruitment as well as lung eotaxin and IL-5 production." (PMID 22762009, 2012). "Tissue eosinophilia during the allergic process is mainly coordinated by interleukin (IL)-5 and the CC chemokine CCL11/eotaxin both in experimental animals and human subjects." (PMID 23316161, 2012). "Anti-IgE or anti-IL-5 antibody only showed minimal beneficial effects on symptoms, eosinophilia and peak nasal inspiratory flow (PNIF)." (PMID 22927869, 2012). "CCL11 KO mice have reduced numbers of these cells in the colon and double knockout mice of CXCL11 and IL-5 completely lack eosinophilia." (PMID 23053395, 2012). "For example, immune responses classically mediated by the Th2 cytokine IL-5 (eosinophilia and eosinopoiesis) were reported in the first weeks of infection." (PMID 22347513, 2012). "IL-5 overexpression induced striking airway eosinophilia, along with mucus metaplasia and subepithelial fibrosis." (PMID 22315625, 2012). "In many of these conditions, eosinophilia is triggered by aberrantly produced eosinophilopoietic growth factors, such as IL-5 or GM-CSF." (PMID 23282419, 2012). "The release of IL-5 and subsequent tissue eosinophilia in the airways during allergic inflammation induced by OVA is largely dependent on the early IL-4." (PMID 23316161, 2012). "Eosinophilia induced by parasitic infection is dependent on interleukin-5 produced by Th-2 subset of CD4+ helper T cells." (PMID 23109965, 2012). "CF prevented the development of AHR, lung inflammation, and airway eosinophilia and decreased the level of Th2 cytokines (IL-5 and IL-13) in the BALF." (PMID 22439901, 2012). "The induction of eosinophilia during T. muris infection is under the control of IL-5 and the chemokine CCL11 which work in synergy to recruit eosinophils." (PMID 23053395, 2012).
eosinophilia (continued). "We have previously shown this method to induce significant airway hyperresponsiveness to acetylcholine, increased serum IgE, increased eosinophilia and increased Th2 (IL-4, IL-5 and IL-13) cytokine expression." (PMID 22151973, 2011). "Eosinophilia in response to inhalation of A. fumigatus extracts is mediated by Th2 cytokines, as airway recruitment is decreased in the presence of antibodies to IL-5." (PMID 21533200, 2011). "Eosinophilia is driven by allergen-activated Th2 cells that generate large amounts of Th2 cytokines (such as IL-4, IL-5, and IL-13)." (PMID 21772663, 2011). "It is also reported that the CCL20/CCR6 system plays a pivotal role in allergic airway responses such as airway resistance, airway eosinophilia, and production of IL-5 and IgE." (PMID 22013453, 2011). "In our studies, blockade of IL-10 in conjunction with PZQ treatment led to an increase in eosinophilia and adult worm-specific IL-4, IL-5, IFNγ and IL-17A." (PMID 21829367, 2011). "It is likely that enhanced lung eosinophilia in response to A. versicolor is mediated by increased IL-5." (PMID 21533200, 2011). "Many immunological correlates of resistance to re-infection in humans have been reported including IL-5 and eosinophilia, mast cells and IFNγ." (PMID 21829367, 2011). "We now show that CD4–CD19+ MLN B cells from infected, but not naïve, mice are able to transfer a down-modulatory effect on allergy, significantly suppressing airway eosinophilia, IL-5 secretion and pathology following allergen challenge." (PMID 20306466, 2010). "The critical role of IL-5 in eosinophilia has been confirmed by the use of an anti-IL-5 antibody in asthmatic patients, which almost depletes circulating eosinophils and prevents eosinophil recruitment into the airway after allergen." (PMID 20616938, 2010). "Ovalbumin provoked acute allergic inflammation and chronic remodeling of murine airways, evident by airspace eosinophilia, IL-5 up-regulation, and airspace enlargement." (PMID 20796309, 2010). "This pro-allergic capability has been related to their ability to produce significant amounts of IL-5, the critical effector in asthmatic eosinophilia." (PMID 19769993, 2010). "It is possible that the persistent airway wall eosinophilia in this situation reflected an inhibitory effect on trans-epithelial cell migration by the antibody blocking interleukin-5." (PMID 20540713, 2010). "As shown here, CD4−CD19+ B cells from chronically infected mice can indeed suppress airway inflammation in uninfected recipients, reducing bronchoalveolar IL-5, eosinophilia and airway pathology." (PMID 20306466, 2010). "In concordance with results of airway eosinophilia, levels of IL-5 expression in parenchyma cells and lung function were also abolished by treatment with highest doses of retinoic acid." (PMID 19852821, 2009). "In view of the correlation between worm infection and levels of IL-5, which controls eosinophil production, maturation, migration and persistence in the tissues, the pattern of blood eosinophilia was of interest." (PMID 19436745, 2009). "The immune response in clinically asymptomatic individuals is dominated by IL-4, IL-5, IL-10, and IL-13 secretion, IgE and IgG4 antibodies, and peripheral eosinophilia." (PMID 19381284, 2009). "This study suggested that eosinophilia was promoted by at least perforin-dependent cytotoxicity of effector T cells and T-cell production of interleukin-5 (IL-5)." (PMID 19015733, 2008). "Humanised anti-IL-5 antibodies have been developed and a single i.v. infusion of one of these (mepolizumab) markedly reduces blood and sputum eosinophilia for several months." (PMID 18315837, 2008). "In animals, IL-33 treatment induces the expression of IL-4, IL-5 and IL-13 in the lung and intraperitoneal injection of IL-33 induces spleen eosinophilia." (PMID 18315837, 2008).